ZNF395 (zinc finger protein 395)
Description:
Plays a role in papillomavirus genes transcription.
Synonyms: HDRF-2; HDBP-2; PRF-1; HDBP2; PBF; DKFZp434K1210; PRF1; Si-1-8-14
Tractability: PROTAC: ubiquitination databases record sites on it.
Gene: Protein-coding gene on chromosome 8 (28,345,590 to 28,402,701, reverse strand). Ensembl gene ENSG00000186918.
Subcellular location: Cytoplasm; Nucleus
Subcellular location (Human Protein Atlas): Nucleoplasm; Cytosol
Gene Ontology:
Molecular function: cis-regulatory region sequence-specific DNA binding; DNA binding; DNA-binding transcription activator activity, RNA polymerase II-specific; protein binding; RNA polymerase II cis-regulatory region sequence-specific DNA binding; DNA-binding transcription factor activity
Biological process: positive regulation of transcription by RNA polymerase II; regulation of DNA-templated transcription; regulation of transcription by RNA polymerase II
Cellular component: cytoplasm; cytosol; nucleoplasm; nucleus
Genetic constraint (gnomAD): Loss-of-function variants: 20 observed, 53.86 expected, observed/expected ratio (o/e) 0.37, 90% interval 0.26 to 0.54. The upper end of that interval is the gene's LOEUF score, 0.54, which puts it in group 2 of 6, group 1 being the genes least tolerant of losing a copy. Missense variants: 605 observed, 658.2 expected, observed/expected ratio (o/e) 0.92, 90% interval 0.86 to 0.98. Synonymous variants: 295 observed, 272.5 expected, observed/expected ratio (o/e) 1.08, 90% interval 0.98 to 1.19.
Homologues: Orthologues: chimpanzee ZNF395 (99% identical), macaque ZNF395 (96% identical), dog ZNF395 (87% identical), pig ZNF395 (87% identical), rabbit ZNF395 (86% identical), guinea pig ZNF395 (82% identical), rat Zfp395 (82% identical), mouse Zfp395 (82% identical), tropical clawed frog znf395 (62% identical), zebrafish znf395a (38% identical), zebrafish znf395b (33% identical), Drosophila melanogaster Glut4EF (29% identical). Paralogues in human: ZNF704 (31% identical), SLC2A4RG (26% identical).
Diseases named in the same sentence as ZNF395 in open-access papers:
ZNF395 is named in the same sentence as 34 diseases in open-access papers, as found by Europe PMC text mining. Sharing a sentence is not in itself a finding about the gene and the disease. The quoted sentences say what the papers report.
glioblastoma (7 papers, 2009 to 2022). The most malignant astrocytic tumor (WHO grade IV). "In skin cancer and glioblastoma cell lines, ZNF395 promotes cancer-associated gene expression and inflammation, whereas in liver cancer cell lines it appears to inhibit cell migration and invasion." (PMID 33580155, 2021). "ZNF395 is a transcription factor induced by hypoxia and a mediator of the maximal hypoxic induction of proinflammatory cytokines in glioblastoma." (PMID 35565433, 2022). "A potential candidate for a human homolog of PQM-1 is the C2H2-ZF transcription factor ZNF395, which is induced in a lymphoma cell line, and in neuroblastomas and glioblastomas in response to hypoxia." (PMID 33580155, 2021). "The transcription factor ZNF395 was found to be overexpressed in various tumors including glioblastomas particularly in the network of a hypoxic response pointing to a functional role of ZNF395." (PMID 26229239, 2015). "ZNF395 was also described as a hypoxia-inducible gene in various glioblastoma, as well as other tumor cell lines, and was found to be activated by cyclic and chronic hypoxia." (PMID 26229239, 2015). "These include previously identified HIF-1 target genes such as ANKRD37, STC-2, and STC-1, as well as COL5A1 induced by hypoxia in the ventricle, ZNF395 regulated by hypoxia in glioblastoma, and TMEM45 in hematopoietic stem cells." (PMID 25122487, 2014). "ZNF395 is expressed in hypoxia-induced glioblastoma cell lines and in the blood vessels of adult glioblastoma tissues." (PMID 24599008, 2014). "Correlatively, ZNF395 was found to be upregulated as part of a response to hypoxia in glioblastomas and neuroblastomas and in adipocytes." (PMID 24086395, 2013). "TREM1 and ZNF395 expression were both mostly expressed in proximity of multilayered blood vessels of glioblastoma." (PMID 19536297, 2009). "Notably, in glioblastomas and neuroblastomas, ZNF395 was among few upregulated genes that were characteristic for a hypoxic response and associated with disease outcome." (PMID 24086395, 2013). "RNA expression patterns for TREM1 and ZNF395 were analyzed in situ on glioblastoma sections." (PMID 19536297, 2009). "A contribution of ZNF395 to the development of an inflammatory tumor microenvironment is further supported by the finding that ZNF395 specific mRNA was detected in microvesicles present in the blood from GBM patients and hypoxic glioblastoma cells." (PMID 26229239, 2015). "In contrast, ZNF395 and KISS1R expression and their hypoxia induction were observed in all four glioblastoma cell-lines, while TNFAIP3 was hypoxia-inducible in LN229 and LNZ308." (PMID 19536297, 2009).
Huntington disease (4 papers, 2009 to 2021). Huntington disease (HD) is a rare neurodegenerative disorder of the central nervous system characterized by unwanted choreatic movements, behavioral and psychiatric disturbances and dementia. "ZNF395 is a transcription factor that binds to the promoter of the Huntington Disease (HD) gene." (PMID 19536297, 2009). "The CR3 of ZNF395 is necessary for sequence-specific DNA-binding to a CG-rich element present in HPV8 and in the Huntington disease gene promoter." (PMID 24086395, 2013).
breast carcinoma (3 papers, 2015 to 2021). "As an RNA‐binding protein, TARBP2 enhances invasion and metastatic colonization by directly binding APP and ZNF395 transcripts, thereby post‐transcriptionally enhancing their decay rate in breast cancer." (PMID 30657254, 2019). "These genes were found to be strongly upregulated upon sh-mediated suppression ZNF395 in breast cancer MDA-LM2 cells under normoxic conditions." (PMID 26229239, 2015). "Transcripts for ZNF395 and APP (amyloid precursor protein) were identified as targets of the metastasis associated protein TARBP2 in the highly metastatic breast cancer cell line MDA-LM2." (PMID 26229239, 2015).
clear cell renal cell carcinomas (3 papers, 2015 to 2024). "Increased expression of ZNF395 could be associated with a poor prognosis in patients with osteosarcomas, Ewing sarcomas, and neuroblastomas and may also play a role in the pathogenesis of clear cell renal cell carcinoma (ccRCC)." (PMID 26229239, 2015). "An upregulation of ZNF395 in clear cell renal cell carcinomas (ccRCC) was observed by several groups." (PMID 26229239, 2015).
liver cancer (3 papers, 2014 to 2020). An epithelial or non-epithelial malignant neoplasm that arises from the liver. "Therefore, the effects of ZNF395 on the development and progression of liver cancer and the mechanism underlying those effects should be investigated." (PMID 24599008, 2014). "In contrast, the tumor suppressor role of ZNF395 was proven in liver cancer, since the overexpression of miR-525-3p downregulated ZNF395, which promoted cancer cell migration and invasion." (PMID 32796700, 2020). "The clinical analysis indeed confirms the inverse correlation of miR-525-3p and ZNF395 in liver cancer." (PMID 27411336, 2016). "The authors show that miR-525-3p, which is overexpressed in liver cancer, promotes liver cancer cell migration and invasion by targeting and down-regulating ZNF395 expression." (PMID 27411336, 2016). "We report for the first time that ZNF395 is frequently down-regulated in liver cancer tissues and that miR-525-3p can specifically target the ZNF395 3′UTR." (PMID 24599008, 2014). "Over-expression of ZNF395 can inhibit liver cancer cell migration and invasion, while restoration of ZNF395 inhibits miR-525–mediated liver cancer cell migration and invasion." (PMID 24599008, 2014). "RANBP10, IRF1 and ZNF395 were found to be down-regulated in liver cancer tissues, while the expression levels of NACC1 and MLST8 remained unchanged." (PMID 24599008, 2014). "ZNF395 is a direct functional target gene of miR-525-3p; miR-525-3p promotes liver cancer cell migration and invasion by down-regulating the expression of ZNF395." (PMID 24599008, 2014). "High expression of ZNF395 can significantly inhibit while knockdown of ZNF395 expression can markedly enhance the migration and invasion of liver cancer cells, suggesting that ZNF395 suppresses metastasis in liver cancer." (PMID 24599008, 2014). "In conclusion, miR-525-3p promotes liver cancer cell migration and invasion by directly targeting ZNF395, and the fact that miR-525-3p and ZNF395 both play important roles in liver cancer progression makes them potential therapeutic targets." (PMID 24599008, 2014). "ZNF395 was significantly down-regulated in liver cancer tissues, with down-regulation observed in 62% of liver cancer tissues." (PMID 24599008, 2014). "Down-regulation of ZNF395 can mediate miR-525-3p induced liver cancer cell migration and invasion." (PMID 24599008, 2014). "Additionally, miR-525-3p is frequently up-regulated in liver cancer tissues and regulates liver cancer cell migration and invasion by down-regulating the expression of ZNF395." (PMID 24599008, 2014). "However, a recent study reveals the tumor suppressor role of ZNF395 in liver cancer." (PMID 27411336, 2016). "Zinc finger protein 395 (ZNF395) is the direct functional target gene for miR-525-3p, and it is frequently down-regulated in liver cancer tissues." (PMID 24599008, 2014). "ZNF395 has not been previously reported to be involved in liver cancer or tumor metastasis." (PMID 24599008, 2014).
astrocytoma (2 papers, 2013 to 2015). "To address these conflictive observations, we investigated the role of ZNF395 in the expression of proinflammatory cytokines in the astrocytoma cell line U87-MG under hypoxia." (PMID 26229239, 2015). "We confirmed the contribution of ZNF395 in the IFN-α-dependent stimulation of ISG56 and IFI44 expression in the astrocytoma cell line U87-MG." (PMID 24086395, 2013).
glioma (2 papers, 2009 to 2025). A benign or malignant brain and spinal cord tumor that arises from glial cells (astrocytes, oligodendrocytes, ependymal cells). "In glioma, CCL20 upregulated by ZNF395 enhanced M2 macrophage polarization which in turn promoted the proliferation of glioma cells." (PMID 39985603, 2025). "The hypoxia regulation of several new genes comprised in this cluster including ZNF395, TNFAIP3, and TREM1 was experimentally confirmed in glioma cell lines and primary monocytes exposed to hypoxia in vitro." (PMID 19536297, 2009).
Obesity (2 papers, 2021 to 2022). Accumulation of substantial excess body fat. "For those 12 genes, six of them (DDO, SEPT9, TMEM45B, RXRα, ZNF395 and AHRR) were previously reported to be implicated in the obesity or related diseases and the rest six were novel (PACRG, LINC00494, KLHL4, DTX1, VCX3A and VSTM1)." (PMID 35568907, 2022).
osteosarcoma (2 papers, 2005 to 2014). A usually aggressive malignant bone-forming mesenchymal neoplasm, predominantly affecting adolescents and young adults. "Papillomavirus binding factor (PBF) or zinc finger protein 395 is a transcription factor associated to a poor prognosis in patients with osteosarcoma, an aggressive bone cancer that predominantly affects adolescents." (PMID 25471943, 2014).
renal cell carcinoma (2 papers, 2013 to 2016). "Although ZNF395 has been repeatedly identified as a significant marker of renal cell carcinoma, very little functional characterization of this TF has been performed." (PMID 27833659, 2016). "Gene expression arrays repeatedly found the expression of the cellular factor ZNF395 (previously called PBF for Papillomavirus binding factor) significantly increased in various cancers such as renal cell carcinomas, osteosarcomas and Ewing sarcomas." (PMID 24086395, 2013).
skin cancer (2 papers, 2013 to 2015). "Since we have observed previously that overexpression of ZNF395 induced cell growth inhibition, we generated a cell line, based on the skin cancer derived RTS3b line, allowing the inducible expression of ZNF395 controlled by doxycycline (Dox)." (PMID 24086395, 2013).
breast tumors (1 paper, 2016). "We further characterized several transcription factors linked to a large number of enhancers in each tumor type, including GATA3 in non-basal breast tumors, HOXC6 and DLX1 in prostate tumors, and ZNF395 in kidney tumors." (PMID 27833659, 2016).
HCMV infection (1 paper, 2013). "Similarly, ZNF395 expression was downregulated in CD8+ T lymphocytes in the acute phase of HCMV infection compared to naïve CD8+ T-cells." (PMID 24086395, 2013).
intraepithelial neoplasia (1 paper, 2024). A precancerous neoplastic process that affects the squamous, glandular, or transitional cell epithelium without evidence of invasion. "In pancreatic cancer, downregulation of ZNF395 caused by loss of chromosome 8p is a critical step in driving progression of intraepithelial neoplasia into invasive carcinoma." (PMID 39348078, 2024).
kidney cancer (1 paper, 2016). Primary or metastatic malignant neoplasm involving the kidney. "Some of the TENET-identified TFs in KIRC (TFEC, RUNX1, ZNF395) have been previously linked to kidney cancer." (PMID 27833659, 2016). "We also revealed important TFs linked to enhancers activated in kidney cancer and further identified de novo motifs enriched in enhancers linked to ZNF395." (PMID 27833659, 2016). "ZNF395, which encodes a protein having one C2H2-type zinc finger domain, is overexpressed in various tumors including kidney cancer and has been reported to be induced by hypoxia involved in IKK signaling." (PMID 27833659, 2016).
kidney tumors (1 paper, 2016). "To follow up on our identification of TFs linked to hundreds of enhancers in kidney tumors, we further studied enhancers linked to ZNF395." (PMID 27833659, 2016). "We also discovered de novo motifs enriched in enhancers linked to ZNF395 in kidney tumors." (PMID 27833659, 2016).
leukemia (1 paper, 2016). A malignant (clonal) hematologic disorder, involving hematopoietic stem cells and characterized by the presence of primitive or atypical myeloid or lymphoid cells in the bone marrow and the blood. "Although ZNF395 ChIP-seq data obtained using an antibody to the endogenous protein have not been published, ChIP-seq data obtained using a GFP antibody and K562 leukemia cells harboring a GFP-tagged ZNF395 are available as part of the ENCODE project." (PMID 27833659, 2016).
Simpson-Golabi-Behmel syndrome (1 paper, 2015). Simpson-Golabi-Behmel syndrome is a rare X-linked multiple congenital anomalies syndrome, characterized by pre- and postnatal overgrowth, distinctive craniofacial features, variable congenital malformations, organomegaly and an increased tumor risk. "A hypoxic induction of ZNF395 was also detected in mature SGBS (Simpson-Golabi-Behmel syndrome) adipocytes." (PMID 26229239, 2015).
tuberculosis (1 paper, 2022). A chronic, recurrent infection caused by the bacterium Mycobacterium tuberculosis. "ZNF395 is an activator of a subset of IFN-stimulated genes, and RAB33A is a T-cell regulatory molecule associated with tuberculosis that has been suggested to be involved in disease processes." (PMID 36557693, 2022).
virus infection (1 paper, 2013). "A role of ZNF395 in the innate immune response against virus infections is supported by several reports." (PMID 24086395, 2013).
cancer (14 papers, 2009 to 2024). A tumor composed of atypical neoplastic, often pleomorphic cells that invade other tissues. "HDBP2—more commonly known as ZNF395—has also been implicated in various human cancers, although in conflicting roles." (PMID 27527215, 2016). "The results of the microarray also revealed an increased expression of four genes known to be associated with cancer upon induction of ZNF395." (PMID 24086395, 2013). "Loss of the pro-apoptotic gene ZNF395 could thus initiate cancer development." (PMID 39348078, 2024). "Although further analysis is required to determine a functional role of ZNF395 in controlling the expression of these cancer-associated genes, it is possible that ZNF395 may also affect cancer growth by elevating the expression of these genes in particular under conditions of hypoxia." (PMID 24086395, 2013). "Tumor-promoting inflammation is another important hallmark of cancer that sodium selenite treatment reduced by downregulating CD14 and ZNF395 genes." (PMID 36059619, 2022). "On the other hand functional studies and data based on genome wide expression analysis found increased ZNF395 expression in various cancer tissues and are in line with a role of ZNF395 supporting cancer progression." (PMID 28316371, 2017). "For example, ZNF395 is overexpressed in various cancers, including Ewing sarcomas, osteosarcomas and renal cells carcinomas." (PMID 27411336, 2016). "Hypoxia-induced ZNF395 can transcriptionally up-regulate cancer-related genes and interferon-stimulated genes, such as IFIT1/ISG56, IFI44 and IFI16, in an IKK signaling-dependent manner." (PMID 27411336, 2016). "ZNF395 also belonged to the genes upregulated in various cancer cell lines by hypoxia and by overexpression of the hypoxia-inducible transcription factor-1α (HIF-1α)." (PMID 24086395, 2013). "Induced ZNF395 expression led to the upregulation of genes known to play a role in cancer as well as a subset of interferon (IFN)-stimulated genes (ISG) involved in antiviral responses such as IFIT1/ISG56, IFI44 and IFI16." (PMID 24086395, 2013). "The cellular transcription factor ZNF395 has repeatedly been found overexpressed in various human cancers, particularly in response to hypoxia, implying a functional relevance." (PMID 24086395, 2013). "A gene expression array revealed that the genes whose expression was induced by the hypoxia-inducible factor ZNF395 are part of pathways involved in cancer and in the innate immune response." (PMID 24086395, 2013). "The impact of reintroducing ZIC4 on innate immune response in our model system could also be seen with other zinc finger proteins, like BNC2 (human basonuclin 2) and ZNF395 in cancer cells." (PMID 39266576, 2024). "A putative metabolic impact of ZNF395 on cancer development should therefore be analyzed." (PMID 33580155, 2021). "Its overexpression in cancer tissues may partially be based on the fact that ZNF395 is a hypoxia induced gene." (PMID 28316371, 2017). "Furthermore, the finding that the target genes of ZNF395 are involved in the innate immune response and cancer, implies that ZNF395 may support inflammation and cancer progression under hypoxia, which deserves further investigation." (PMID 24086395, 2013). "For example, ZNF395 expression is induced under hypoxic stress in GBM, where it up-regulates interferon-stimulated and cancer-related genes, promoting inflammation and cancer progression." (PMID 32796700, 2020). "Little is known on the potential role of the other two hypoxia inducible genes, ZNF395 and KISS1R, in cancer." (PMID 19536297, 2009). "Some of them have also been shown to be involved in cancer progression such as STC1 and ZNF395." (PMID 25122487, 2014).